ERBB2 (erb-b2 receptor tyrosine kinase 2)
Diseases named in the same sentence as ERBB2 in open-access papers (continued):
Sharing a sentence is not in itself a finding about the gene and the disease.
breast cancer (continued). "Our research focuses on novel cancer preventative and therapeutic strategies targeting the ErbB2-overexpressing/ErbB2-positive (ErbB2+) breast cancer subtype, which is associated with poor prognosis and therapeutic resistance." (PMID 28947975, 2017). "For example, in HER2-overexpressing breast cancers, increased expression of ERBB2 gene is associated with 17q21 copy number gain." (PMID 28415743, 2017). "We have previously shown that loss of p110α in the Mouse Mammary Tumor Virus (MMTV)-ErbB2-IRES-Cre (NIC model) results in abrogation of mammary tumor development over an initial 8-month observation period." (PMID 28783168, 2017). "Previous studies showed that ERBB2 amplification frequently associates with DNA hypermethylation in human breast cancers." (PMID 28781955, 2017). "We previously defined phospho-Ser294 PRs as major transcriptional drivers of gene programs significantly associated with HER2/ERBB2 signaling in breast cancers." (PMID 28412963, 2017). "STOM encodes a major lipid-raft protein stomatin, which locates at the plasma membrane of multiple cell types, and is associated with non-small cell lung cancer and erb-b2 receptor tyrosine kinase 2-positive breast cancer." (PMID 29237456, 2017). "Data from both preclinical models and clinical trials support lapatinib as a preventative agent for women at risk for erbB-2/Her2+ breast cancers." (PMID 28061785, 2017). "ERBB2 is overexpressed in up to 20–30% of human breast cancers (BCs), and it is associated with aggressive disease." (PMID 29100552, 2017). "Both mutations activate ErbB2 by either affecting its auto-phosphorylation or phosphorylation of downstream substrates in breast cancer cells." (PMID 28271309, 2017). "The human epidermal growth factor receptor-2 (Her2, ErbB2) is frequently overexpressed in human breast cancer, which is associated with poor survival." (PMID 27791982, 2017). "ErbB2/HER2/Neu is a receptor tyrosine kinase that is overexpressed in 25–30% of human breast cancers, usually associated with amplification of the ERBB2 gene." (PMID 28369073, 2017). "For example, in ErbB2-positive or KRAS mutated breast cancers, PTEN-null tumors are solely dependent on p110α." (PMID 28783168, 2017). "For examples, using ERBB2 (HER2), a frequently amplified gene in breast cancer, to query the breast cancer network, we associated the gene to lipid biosynthetic process." (PMID 27836980, 2017). "In this regard, implementation of phenformin as a cancer preventative in women who are at risk for developing ErbB2+ breast cancer would provide substantial clinical benefits." (PMID 28947975, 2017). "The introduction of Tz therapy and, more recently, of the first successful ERBB2-targeted antibody–drug conjugate (ADC), trastuzumab emtansine (T-DM1, Kadcyla, Genentech) markedly improved the poor prognosis associated with ERBB2-amplified breast cancers." (PMID 28947957, 2017). "Overexpression of ErbB2 is found in about 25%–30% of human breast cancers, and is associated with tumorigenesis, cancer progression and poor prognosis." (PMID 28881779, 2017). "The proto-oncogene, c-erbB2 encodes the human epidermal growth factor receptor 2 (HER2), which is overexpressed and/or amplified in several human malignancies, including 25–30% of breast cancers." (PMID 28533703, 2017). "Overall, our results provide evidence for buformin as an effective anti-cancer drug that selectively targets TICs, and present a novel prevention and/or treatment strategy for patients who are genetically predisposed to erbB-2-overexpressing breast cancer." (PMID 28193239, 2017). "Our study showed calcifications in breast cancers are associated with high levels of mRNA expression of ERBB2 and decreased immune system activity." (PMID 28900139, 2017). "Neratinib has been shown to have clinical activity in breast cancers with ERBB2 amplifications or mutations." (PMID 29163826, 2017).
breast cancer (continued). "It has also been shown that lapatinib-induced inhibition of the crosstalk between EGFR/ErbB2 and ER pathways in ErbB2+/ER+ breast cancers is closely linked to its anti-tumor efficacy." (PMID 28938602, 2017). "Abnormal expression of this receptor is linked with malignant transformation, with breast cancer being the most common type of ErbB2-driven malignancy." (PMID 27542246, 2016). "Because women with high MD have an increased risk factor to develop breast cancer, it is necessary to investigate the overexpression of ERBB2 at high stiffness further." (PMID 27383056, 2016). "It encodes within the ERBB2/Her2 gene, which is amplified in HER2 positive breast cancer and cause the clinically genomic aberration." (PMID 27650797, 2016). "Among those significant mutations and CNVs associated with a CDH1 alteration, ERBB2 was the most well-known oncogene associated with high grade breast cancer." (PMID 27811364, 2016). "With the advent of massively parallel sequencing, mutations in the sequence of the ERBB2 gene were found in a limited fraction (<1%) of breast cancers." (PMID 27602491, 2016). "In breast cancer patients, amplification and/or overexpression of ErbB2 is strongly associated with worse prognosis and a higher incidence of metastases." (PMID 26967059, 2016). "Overexpression of ErbB2 is found in 25%-30% of human breast cancers and is associated with tumor progression and poor prognosis." (PMID 27564098, 2016). "PTEN down-regulation and ERBB2 expression seems also to be caused by AKT activation (PI3K/AKT/PTEN pathway) in feline mammary tumors, as it occurs in human breast cancer." (PMID 29056725, 2016). "Clinical studies have indicated an increased expression of Epidermal Growth Factor Receptor (EGFR/ERRB1) and its family member ERBB2 in breast cancers which are associated to tumor development, progression." (PMID 27564112, 2016). "This mutation rate is far above the ≤1% ERBB2 mutation rate globally reported for breast cancer in The Cancer Genome Atlas." (PMID 27602491, 2016). "Abnormally activated ErbB Family receptors (EGFR [ErbB1], HER2 [ErbB2], ErbB3 and ErbB4) and estrogen receptors (ER) are frequently implicated in breast cancer, making these potential therapeutic targets." (PMID 26835225, 2016). "HIF1A activation under normal oxygen tension has been linked to anoikis resistance of breast cancer cells driven by ERBB2 oncogene, and circulating breast tumor cells from patients with metastatic breast cancer." (PMID 27495308, 2016). "PKCα has been functionally associated with ErbB2, the main dimerization partner for ErbB3, and was found to be an essential mediator of ErbB2-driven breast cancer invasiveness." (PMID 27351228, 2016). "Amplification and elevated expression of the erbB2 proto-oncogene is associated with poor outcome in patients with breast cancer." (PMID 27409835, 2016). "Human epidermal growth factor receptor 2 (HER2 or ErBb2) is a receptor tyrosine kinase overexpressed in 20-30% of breast cancers and associated with poor prognosis and outcome." (PMID 26918448, 2016). "The proto-oncogene HER2 (ERBB2) is amplified in approximately 20 % of breast cancers and is associated with a number of adverse prognostic factors, such as increased proliferative indices, metastasis and recurrence." (PMID 27184134, 2016). "ERBB2 is amplified and overexpressed in 20% to 30% of human breast cancers, and it is often associated with aggressive disease and poor prognosis." (PMID 27863425, 2016). "Pathologic complete response (pCR) after neoadjuvant chemotherapy for breast cancer is associated with improved prognosis in aggressive tumor subtypes, including ERBB2- positive tumors." (PMID 27576528, 2016). "The mutation p.V777L in exon 20 of the ERBB2 gene is already described as an activating mutation that likely drives tumorigenesis in breast cancer and it can be found in 1.6–2.0% of breast cancer patients and in about 6.0% of ERBB2-mutated patients." (PMID 27034166, 2016).
breast cancer (continued). "ErbB2 Receptor Tyrosine Kinase 2 (ErbB2, HER2/Neu) is amplified in breast cancer and associated with poor prognosis." (PMID 27765041, 2016). "ERBB2 +2246A/G polymorphism (amino acid substitution: isoleucine to valine) is associated with an increased familial breast cancer risk." (PMID 27008699, 2016). "We demonstrate that a subset of these EMT-associated genes is predictive of prognosis within the ERBB2 subtype of human breast cancers." (PMID 26883193, 2016). "Breast cancer is currently one of the leading mortality causes in women, and acquired resistance to ErbB2-targeted therapies is a major obstacle in its treatment." (PMID 27542246, 2016). "Our model is based on our analyses of a cohort of mice that are characterized by heterogeneous susceptibility to ERBB2-positive breast cancers." (PMID 25853295, 2015). "We report a global scenario of complex interactions at cellular and systemic levels that accounts for the heterogeneity in ERBB2-breast cancer behavior and susceptibility." (PMID 25853295, 2015). "We report a global scenario of complex interactions at cellular and systemic levels that accounts for the heterogeneity in ERBB2-positive breast cancer behavior and susceptibility." (PMID 25853295, 2015). "HER2/ErbB2/Neu is overexpressed in about 30% of human breast cancers and is associated with poor prognosis." (PMID 25592291, 2015). "Here, we present a model in which there are complex interactions at different cellular and systemic levels that account for the heterogeneity of susceptibility to and evolution of ERBB2-positive breast cancers." (PMID 25853295, 2015). "The human epidermal growth factor receptor 2 (HER2), also known as ErbB2, an orphan receptor tyrosine kinase, is implicated in enhanced breast cancer cell proliferation and aggressive tumorigenic behavior." (PMID 26222911, 2015). "We observed that ERBB2-induced breast cancer heterogeneity was associated with different molecular subphenotypes at the level of both the tumor pathophenotypes and the prognosis clusters." (PMID 25853295, 2015). "We considered different clinical manifestations of ERBB2-positive mammary cancer as the result of multiple associations at different molecular levels from a systems biology perspective." (PMID 25853295, 2015). "Here, we tackled this question with a systems biology approach in a heterogeneous population of mice that developed ERBB2-positive mammary cancer with varied susceptibility and progression." (PMID 25853295, 2015). "Anti-ErbB agents are becoming the cornerstone therapeutics for the management of cancers that overexpress hyperactive variants of ErbB receptors, in particular ErbB2-positive breast cancer and non-small cell lung carcinomas." (PMID 25699077, 2015). "ERR-α is regulated by ErbB2/Her2 signaling, and is associated with poor outcomes in breast cancer patients." (PMID 25961905, 2015). "Crosstalk between ERBB2 and estrogen signaling has long been observed in breast cancer and ERBB2 overexpression has been associated with estrogen-independent growth of ER+ breast cancer cell lines and resistance to endocrine therapy in breast tumors." (PMID 26235388, 2015). "In particular, erbB-2 is amplified/overexpressed in approximately 30% of human breast cancers, and this effect has been associated with poor prognosis and therapeutic resistance." (PMID 25853264, 2015). "The methylation status of the Per genes was also linked to increased expression of ERBB2, the gene used to help classify breast cancers by type and a prognostic marker that negatively correlates with disease-free survival and overall survival." (PMID 26220712, 2015).
breast cancer (continued). "The ErbB signalling pathway has been found to influence in proliferation, migration, differentiation and apoptosis in cancer and overexpression of ERBB1 and ERBB2 have been implicated in head and neck and breast cancers." (PMID 25886033, 2015). "Based on this discovery we developed a mouse model of breast cancer where an activating mutation in the ErbB2 oncogene was combined with loss of LKB1 expression (LKB1−/−NIC mice)." (PMID 25436981, 2014). "ERBB2 mutations have been described in non-small cell lung cancer, breast cancer, gastric cancer and colorectal cancer." (PMID 25536104, 2014). "The ErbB2 oncogene is amplified in up to 30% of human breast cancers and is associated with poor patient prognosis in response to chemotherapeutic agents." (PMID 24658544, 2014). "Gene amplification and/or overexpression of the human epidermal growth factor receptor 2 (HER2, ErbB-2) have been identified in 20-25% of breast cancers and are associated with poor prognosis." (PMID 25179116, 2014). "Molecular markers such as progesterone receptor, estrogen receptor, and ErbB2 have been associated with the five major subtypes of breast cancer: luminal A, luminal B, ErbB2+/ER-, basal-like, and normal breast-like." (PMID 24628760, 2014). "Up to 30 % of breast cancers overexpress human epidermal growth factor receptor 2 (HER2, c-erbB2), and HER2 positivity is associated with significantly worse outcomes than HER2-negative breast cancer." (PMID 23563986, 2014). "Using our mouse model of spontaneous breast cancer promoted by loss of LKB1 expression in an ErbB2 activated model; referred to as LKB1−/−NIC mice, we evaluated the effect of novel therapies in vivo on primary tumors." (PMID 25436981, 2014). "Overexpression of flotillin-2 in breast cancer was shown to be associated with the clinical stage, T and M classification, histological differentiation and receptor tyrosine kinase ErbB2 expression levels." (PMID 24709906, 2014). "Other specific gene amplifications, for instance in breast cancer such as ERBB2 or MDM2 are associated with high grade cancer and have strong prognostic significance." (PMID 25013904, 2014). "A positive correlation between the expression of BCAR1/p130Cas and ErbB2 has been found in human breast cancers and the co-expression of these two genes is associated with shorter overall survival and a higher risk of developing distant metastasis." (PMID 25606587, 2014). "These included CDH1, the gene which encodes E-cadherin, and ERBB2, the gene which is amplified in 20-35% of breast cancer patients, both of which are known to be involved in breast tumorigenesis." (PMID 24641801, 2014). "Overexpression/amplification of HER2/ERBB2 in breast cancer, resulting in HER2-positive subtypes, is associated with very poor prognosis compared with HER2-negative breast cancer." (PMID 23563986, 2014). "In some cases these drugs bind primary oncogenic drivers such as ErbB2, which is overexpressed in the HER2amp breast cancer subtype, or ErbB1, which is mutated in non-small cell lung cancer." (PMID 24655548, 2014). "Human epidermal growth factor receptor 2 (HER2/ERBB2) is a proto-oncogene and high expression of HER2 is associated with poor prognosis in several types of cancer including breast cancer." (PMID 24693969, 2014).
breast cancer (continued). "Amplification and overexpression of HER2 (also named ErbB2) receptor tyrosine kinase, detected in 20–30% of breast cancer, are associated with a poor clinical patient outcome, including lymph node metastasis, shorter survival, and shorter time to recurrence." (PMID 24707474, 2014). "Amplification of human epidermal growth factor receptor 2 (ErbB2 or HER2) occurs in approximately 20 % of breast cancers and is associated with poor prognosis." (PMID 24292401, 2014). "Our own unpublished data shows that there is an association between high plasma LDL level and ErbB2 positive breast cancer." (PMID 24428917, 2014). "In a transplantation model of mammary carcinoma, loss of Par3 cooperates with ErbB2 to destabilize E-cadherin junctions and aberrantly activate Tiam1-Rac-GTP signaling." (PMID 23771628, 2014). "Further, somatic mutations in the kinase domain of ErbB2 were discovered in various solid cancers including lung and breast carcinomas." (PMID 25238247, 2014). "ERBB2 overexpression or amplification was initially discovered in approximately one third of human breast cancers and is associated with more aggressive tumors and poorer outcome." (PMID 23630663, 2013). "The highest mutational frequency for all of the genes assessed in this study (PIK3CA and/or PIK3R1 and/or AKT1) was observed in HR+/ERBB2- tumors (133/289; 46.0%), while mutations were observed in up to 28% of cases in other breast cancer subtypes." (PMID 24229379, 2013). "The FLOT2-mediated stabilization of ErbB2 has been associated with tumorigenesis in stage I/II breast cancer tissues, which is reflected by reduced p-ErbB2 and p-Akt levels and hyperactivity of the PI3K/AKT/mTOR pathway in breast tumors." (PMID 23945257, 2013). "High expression of the glutamine cluster was associated with reduced survival in ERBB2-enriched and luminal B subtypes, and this association held true when looking at all breast cancer patients." (PMID 24304688, 2013). "Mammary tumor onset and multiplicity were examined in ErbB2 transgenic mice thatwere deficient in mammary epithelial cell COX-2 (COX-2MECKO) comparedto wild type (WT) mice." (PMID 24004819, 2013). "The ERBB2 (Her2/Neu) gene encodes a tyrosine kinase receptor whose abnormal activity is linked to oncogenesis in breast cancer." (PMID 23421821, 2013). "Here we show that loss of LKB1 in ErbB2-mediated breast cancer is sufficient to promote the Warburg effect." (PMID 24280377, 2013). "Concerning SV studies in human breast cancer, the rs1801200 ERBB2 polymorphism (detected in exon 17), which corresponds to the Ile655Val mutation in human erbB-2, was extensively investigated as a risk factor for breast cancer by several authors." (PMID 24386251, 2013). "We believe that further efforts should be made in order to extend the studies of these cat erbB-2 mutations in cat mammary lesions and to analyse their importance in cat mammary tumour evolution." (PMID 24386251, 2013). "HER2/Neu (ErbB-2) overexpression, which occurs in 15–20% of breast cancer cases, is associated with better response to treatment with the drug trastuzumab." (PMID 24278211, 2013). "To investigate molecular mechanisms contributing to the pro-growth, invasive phenotype of LKB1-deficient ErbB2-positive breast cancer cells, we examined primary tumors using a reverse phase protein array (RPPA)." (PMID 24280377, 2013). "In fact, our reconstructed model identified two feedback mechanisms which were experimentally proved by other researchers to cause Trastuzumab resistance in ERBB2 overexpressing breast cancer cells." (PMID 23829771, 2013). "ErBb2 mouse models show remarkable morphological resemblance to some formsof human breast cancer and accurately recapitulate the hallmark changes associated withthe early stages of human breast cancer." (PMID 24004819, 2013). "These truncated ERBB2 proteins have been predominantly found in breast cancers and cause resistance to trastuzumab." (PMID 23630663, 2013).